PLK1 (polo like kinase 1)
Diseases named in the same sentence as PLK1 in open-access papers (continued):
Sharing a sentence is not in itself a finding about the gene and the disease.
tumor (continued). "Inhibition of PLK1 reduces the phosphorylation of FBW7, preventing its autoubiquitination and proteasome degradation, thereby promoting the degradation of MYC and reducing tumor cell proliferation while increasing apoptosis." (PMID 40612941, 2025). "In this investigation, we found that SHCBP1 affects tumor cell EMT; hence, its modulation of PLK1 activation may also affect EMT." (PMID 39949984, 2025). "Similar trends were observed in the orthotopic isograft tumor model, where the treatment of Bobcat339, HPPE, or PLK1-IN-10 markedly reduced the bioluminescence intensity of labeled 3LL cells in the mouse lung, accompanied to decreased number and size of tumor burdens." (PMID 40665337, 2025). "UCNPs-Cas9@PEI targeting the PLK-1 gene successfully inhibited cancer cell proliferation and tumor growth without noticeable abnormalities or appreciable organ damage to major organs from different groups of mice." (PMID 40214585, 2025). "Lastly, a xenograft tumor model was established in nude mice, where lentivirus-mediated overexpression of SAMD5 and/or PLK1 was introduced into tumors, and the dynamic effects of SAMD5/PLK1 were investigated." (PMID 39524172, 2024). "We wanted to confirm the role of PLK1 and MISP in the tumor growth of iCCA cells." (PMID 38057358, 2024). "The role of PLK1 and MISP in regulating tumor cell adhesive functions remains to be determined." (PMID 38057358, 2024). "The authors of this study could show approximately 70% gene editing in vivo at the polo-like kinase 1 (PLK-1) target gene, which in turn resulted in tumor cell death, reduced tumor growth, and extended animal survival." (PMID 39000440, 2024). "In BC, PLK1 signalling has been shown to cooperate in ER‐dependent gene transcription, and its genetic or pharmacologic inhibition led to G2/M arrest in TNBC cell lines and to tumour shrinkage in CCND1‐driven PDX models of acquired palbociclib resistance." (PMID 38264947, 2024). "Moreover, SHCBP1, PLK1, and PHH3 (Ser10) expression in tumour cells gradually increased with increasing paclitaxel concentration, further demonstrating higher SHCBP1 expression in M phase." (PMID 38365687, 2024). "Finally, we show that EYA-mediated dephosphorylation of PLK1 supports PLK1 function during mitotic progression, while treatment with an EYA phosphatase inhibitor potently elicits cell death in tumour cells expressing EYA4 and/or EYA1." (PMID 38360978, 2024). "Accordingly, multiple logistic regression confirmed that age was a significant predictor of PLK-1 expression, independent of covariates such as sex, tumor grade, or treatment with biological therapy (p = 0.029)." (PMID 39857637, 2024). "Moreover, the dysregulation of cell-cycle-regulated genes (PLK1, CCNB1, CDKN2A, CCNE2, E2F1, and E2F2) by miR-5100 consistently resulted in upregulation in tumor tissues." (PMID 39590378, 2024). "The inhibition of PLK1 was similarly effective across modified lines, but not as effective as in the sensitive tumor line." (PMID 38667326, 2024). "Consistent with the literature and the many roles of PLK1 in the initiation, progression and completion of mitosis, treatment of HT29 tumor cells with onvansertib led to stabilization of mitotic markers associated with an increased G2/M population by flow cytometry analysis." (PMID 39184047, 2024). "Considering the paired sample differential analysis, expression correlation analysis, immunological and tumour microenvironment correlation analysis, as well as the line chart results, CEMACAM3, LCK, PARP1, PDGFB, PLK1, SEMA7A and SPHK1, were considered as prognostic genes of higher value." (PMID 39656479, 2024). "Furthermore, we validated PLK1 expression using the validation set GSE31210 and uncovered higher PLK1 expression in tumor tissues than that in normal ones." (PMID 37744268, 2023).
tumor (continued). "Since Plk1 is required for tumor cell proliferation, the authors showed that rigosertib induced apoptotic activity against 94 tumor cell lines with a GI50 between 50–200 nM, resulting in tumor cell death by mitotic arrest, demonstrating its potential efficacy." (PMID 37111716, 2023). "Therefore, there are two lines of evidence supporting the role of PLK1 in both immunosuppression in TIME and the anti‐tumor immune response." (PMID 36951624, 2023). "The knockout of PLK1 gene by the CRISPR–Cas9 system can effectively inhibit the proliferation of tumor cells, but there is no suitable vector for in vivo delivery." (PMID 38140096, 2023). "Histological bone involvement: h0, no infiltration of the bone; p1, tumor erosion/infiltration of the bone; plk1, positive lymph nodes." (PMID 37344607, 2023). "To clarify whether PLK1 inhibition can enhance GSC apoptosis and inhibit tumor growth, we used a proteomics-based approach to identify new phosphorylated substrates of PLK1." (PMID 36805592, 2023). "Moreover, the protein levels of PLK‐1, CCNB1, CCNB2, and SIRT2 were observed to decrease in a dose‐dependent manner in tumor tissues following treatment with VS‐5584 in comparison to the control group." (PMID 37658623, 2023). "Concurrent expression of IFITM1, FOXM1, and PLK1 showed a high correlation with tumor formation in primary and advanced LUAD but not in LUSQ." (PMID 37968723, 2023). "EGFR-modified bacterial minicells loaded with siRNA could validly knock down the expression of PLK1, KSP, CDK1, and have the excellent ability to suppress tumor cell proliferation in HCT116 tumor-bearing mice." (PMID 37896250, 2023). "Following that, the top 100 correlated proteins with CEP55 were collected from the GEPIA2 database, where the proteins KIF11, MK167, CDK1, PLK1, and CCNA2 represented the top 5 proteins correlated with CEP55 in the tumor microenvironment that influence immune cells in TME." (PMID 37175004, 2023). "Furthermore, CIP2A regulates polo-like kinase 1 (PLK1) stability and activity, facilitating cell-cycle progression and tumor development." (PMID 36098827, 2022). "In a recent RNA‐seq study, both PLK1 and MYC oncogenes were found overexpressed in two well‐established cOSA cell lines, suggesting a potential implication of this signalling axis in this tumour." (PMID 36054794, 2022). "Moreover, the codelivery system achieved augmented PLK-1 silencing, reinforced apoptosis in MCF-7 cells, and increased penetration and inhibition of tumor spheroids." (PMID 35366888, 2022). "Therefore, 18 pairs of human tumor and adjacent liver tissues were collected, and SETD3 and PLK1 levels were examined by Western blot analysis." (PMID 35912180, 2022). "In order to maintain genomic stability in both healthy and tumor tissues, phosphorylated BLM may subsequently interact with Polo-like kinase 1 via its polo-box domain." (PMID 36499126, 2022). "PLK1 has also been identified as an independent prognostic marker in non-muscle invasive BC, highlighting its importance in tumor progression and the potential for targeted therapies." (PMID 35456552, 2022). "The iLP181 encapsulated psgPLK1 plasmid triggered editing of PLK1 gene with more than 30% in HepG2‐Luc cells and achieved excellent tumor growth suppression without inducing adverse effects." (PMID 37323878, 2022). "We also tested the PLK1 inhibitor volasertib in these three PDXs and did not observe any significant anti-tumor response." (PMID 36505864, 2022). "Therefore, this study demonstrates the vital pro-tumor role of HN1L/AP-2γ/PLK1 signaling axis in ESCC, offering a potential therapeutic strategy for ESCC patients with high HN1L by blocking PLK1." (PMID 36476988, 2022). "The Normalized eXpression (NX) levels of PLK1 were analyzed in various tumor tissues and their corresponding adjacent normal tissues as well as various tumor cells and the corresponding non-tumor cells in the Human Protein Atlas (HPA) database." (PMID 36618405, 2022).
tumor (continued). "Considering the interactions of MAP9 with Plk1 and AURKA, we hypothesized that MAP9 is vital in tumor progression." (PMID 35656338, 2022). "Based on this inference, we screened three key miRNAs (hsa-miR-10b-3p, hsa-miR-23b-3p, and hsa-miR-139-3p) targeting four hub mRNAs (CCNB2, KIF18B, PLK1, and TOP2A) using the correlation analysis, survival analysis, expression analyses in stage, distant metastasis, tumor, and normal tissues." (PMID 33869028, 2021). "Further, PLK1 phosphorylates BRCA1 thus impairing its involvement in homologous recombination, and reported PLK1 expression is higher in TNBC than in both healthy cells and benign tumours." (PMID 33807045, 2021). "Whether PLK1 inhibition could suppress FBXO45-driven HCC xenograft tumors in mice was preliminarily evaluated by analyzing body weight and tumor volume." (PMID 34779401, 2021). "Moreover, a CDC7 inhibitor synergistically enhances the anti‐tumor effect of oxaliplatin in CRC models, demonstrating the potential utility of targeting the PLK1‐MYC‐CDC7 axis in the treatment of oxaliplatin‐based chemotherapy." (PMID 34881526, 2021). "We identify autophagy as a defense mechanism in response to FGFR/PLK1 inhibitor‐induced surge of metabolic stress, which is consistent with recent studies showing that KRAS‐driven tumor cells depend on autophagy to help reduce ROS and to provide substrates to fuel cell metabolism." (PMID 34369083, 2021). "PLK1 promotes Fbw7 phosphorylation, self-ubiquitination, and proteasomal degradation, creating a PLK1-Myc feedforward activation loop in MYC overexpressing tumor cells." (PMID 34503223, 2021). "The observation that tumor cells rather than benign cells are more sensitive to mono‐ and dual treatments suggests the good tolerance of the combination of Plk1 inhibition and 5‐Aza in PCa." (PMID 34051063, 2021). "Plk1 expression was more important in tumors of patients with an intermediate and poor International Metastatic RCC Database Consortium Score (IMDC score) reflecting tumor aggressiveness according to clinical and biological parameters." (PMID 33547392, 2021). "Third, PLK1 blockade was found to trigger DC activation in an indirect fashion by inducing tumor cell death in an immunogenic manner, and vaccination with BI2536-killed tumor cells helped suppress tumor growth." (PMID 34522178, 2021). "Nevertheless, PLK1 blockade cannot induce persisting regression of tumor, since the drug-treated vaccine stimulates a transient not a lasting DC activation unless the vaccine is repeatedly administered." (PMID 34522178, 2021). "This strategy could disrupt the PLK1 gene in U87MG cells‐bearing mice, exhibiting antitumor effects with significant reduction of tumor volume and over 50% downregulation of PLK1." (PMID 34665528, 2021). "Furthermore, PLK1 is a component gene of Overlap66; PLK1 inhibitor significantly reduced OIP5-promoted pRCC cell proliferation in vitro and tumor growth in vivo." (PMID 34503297, 2021). "Downregulation of PLK1 and AURKC was detected in BRDT-knockout and BRDT-silenced tumor tissues." (PMID 33257688, 2020). "However, there are also few genes like PLK1 and MCM4 that are upregulated in both zebrafish and different tumor entities." (PMID 33362851, 2020). "In addition, Plk1 can also modulate oncogenic signaling pathways such as the PI3K-MEKK, or dampening the function of well-known tumor suppressors such as PTEN or REST." (PMID 30862113, 2019). "Third, the TCGA data analysis indicated that PLK1 expression was higher in tumor tissues than in adjacent normal tissues." (PMID 31387297, 2019). "Indeed, overexpression of Plk1 lead to high levels of CIN and this is detrimental for tumor formation when combined with other oncogenes." (PMID 30862113, 2019).
tumor (continued). "Phosphorylated BLM may then bind to Polo-like kinase 1 (PLK1) via its polo-box domain (PBD), further contributing to the maintenance of genomic stability in both healthy and tumor tissues." (PMID 31210839, 2019). "MP-HX downregulated the expression of genes that could promote anti-apoptotic effect, cell cycle progression, tumor development and progression, which include BIRC5, CCNA2, CCNB1, CCNB2, CCNE2, CDK1/2/6, GINS2, HELLS, MCM2/10 PLK1, RRM2 and SKP2." (PMID 30042885, 2018). "At the age of 6–8 weeks we started to inhibit Plk1 by RNAi or by BI6727-treatment in 3 genetically different cohorts (ApcMin/+, Plk1iKD, ApcMin/+Plk1iKD) and monitored the impact on different relevant parameters including tumor development." (PMID 29549256, 2018). "Furthermore, another PLK1 inhibitor, BI6727, maintained broad anti‐tumour activities in several solid tumours." (PMID 27878946, 2017). "Our present results reveal that tivozanib inhibits p-PLK1 and decreases Aurora kinase A in the GBM cells, suggesting that tivozanib might have anti-tumour activity in GICs cells." (PMID 28287096, 2017). "Liposomal mediated delivery of PLK1-siRNA and KSP-siRNA significantly inhibited the PLK1-mRNA and KSP-mRNA expression levels in hepatic cancer cell model and thus enhanced the survival rate of tumor bearing mice." (PMID 34322587, 2017). "In addition to in vitro studies, we demonstrated in in vivo models of RMS and NB that the PLK1 inhibitor BI 2536 cooperates with VCR or eribulin, respectively, to significantly suppress tumor growth compared to either drug alone." (PMID 28881742, 2017). "Abbou and colleagues recently demonstrated preclinical efficacy of PLK1 inhibition in a wide panel of pediatric malignancies independent of tumor histology." (PMID 28036269, 2017). "Unlike Plk1 that promotes cell cycle progression, Plk2 and Plk3 have been identified as tumor suppressors to prevent mitotic catastrophe and preserve genomic integrity." (PMID 27902479, 2017). "As this may affect tumor cell survival and growth, we advocate cautious monitoring of MTORC1 and autophagy readouts in clinical trials with PLK1 inhibitors." (PMID 28102733, 2017). "To determine whether PLK1 is similarly necessary for ATRT-initiating cells, we examined the effects of BI 6727 on the ability of ATRT cells to form tumor spheres." (PMID 29228610, 2017). "However, when G6PD was knocked down, Plk1-enhanced tumor growth of Hep3B xenografts was markedly retarded, suggesting that G6PD was critical for Plk1-regulated tumor growth in mouse model." (PMID 29138396, 2017). "Both ASCs were treated with Plk1 inhibitors BI 2536 and BI 6727 targeting the kinase domain and Poloxin against the PBD for 0, 24, 48, 72 and 96 h at concentrations used for tumor cells and cellular viability was evaluated." (PMID 27713178, 2016). "Our finding that TBK1 functions are necessary for mitosis suggests that the dependency of mutant K-Ras tumour cells on TBK1 for cellular transformation also reflects its roles in directing progression through mitosis, by targeting PLK1 as well as other targets like CEP170 and NuMA." (PMID 26656453, 2015). "Several studies collectively have proven that the (si)RNA-mediated severe inhibition of PLK-1 reduced tumor size without affecting the viability of normal cells." (PMID 26557691, 2015). "More recently, PLK1 has also been shown to contribute to tumor growth via mechanisms that are independent of the cell cycle." (PMID 25557168, 2015). "PLK1 has been the most extensively studied PLK protein and an increasing number of clinical studies describe high levels of PLK1 in tumor cells, and a correlation to aggressive tumor growth and poor survival." (PMID 25557168, 2015). "PLK1 and FOXM1 co-expression was demonstrated in 6/8 (75 %) tumours when analysed by RT-PCR." (PMID 26576650, 2015).
tumor (continued). "We show here that Plk1 inhibition activates the MAPK/Erk and PI3K/Akt pathways, likely responsible for increased p21 in the cytoplasm of HCT116 cells, leading further to the inhibition of apoptosis and survival of treated tumor cells." (PMID 25483104, 2015). "Intriguingly, another in vivo study reported that a liposomal anti-Plk1 siRNA delivery system failed to inhibit tumor growth in a mouse xenograft RCC model." (PMID 26579493, 2015). "In the presence of p21, Plk1 inhibition, along with an induction of mitotic arrest, enhances strikingly the expression of p21 and activates MAPK/Erk and PI3K/Akt pathways, which likely stabilizes p21 in the cytoplasm of treated tumor cells." (PMID 25483104, 2015). "Furthermore, direct cell-cell incubation induces an upregulation of mitotic genes Aurora B and Plk1, cytokine genes IL-6 and IL-8 and the oncogene BCL6 known for their tumor promoting functions." (PMID 26439686, 2015). "Plk1 inhibitors target all rapidly dividing cells irrespective of tumor cells or non-transformed normal but proliferating cells." (PMID 23948487, 2013). "Given the essential role of Plk1 during mitosis, it is conceivable to propose that Plk1 inhibitors target all rapidly dividing cells irrespective of tumor or normal cells, which is consistent with observed adverse effects of Plk1 inhibitors in clinical trials." (PMID 23948487, 2013). "In the study done by McNamara and co-workers, even though the first generation prostrate specific membrane antigen (PSMA) aptamer/ polo-like kinase 1(Plk1)-siRNA (A10-Plk1) chimera inhibited tumor growth, it lacked the ability to be systemically administered." (PMID 21955150, 2011). "Specifically, a group of 40 well-defined genes, classified according to their function, were able to distinguish between 2 different GBM signatures revealing the possible different proliferative potential in high grade GBM tumours (VIM, GLUL, PLK1, HUWE1, RPS4X...)." (PMID 20735813, 2010). "Using the Spearman rank correlation test, a statistically significant positive correlation between PLK-1 expression and primary tumor stage (r = 0.605, P = 0.002) but not metastasis was identified." (PMID 19775446, 2009). "There was a significant positive correlation for PLK3 (P=0.025) but not for PLK1 (P=0.125) expression with histopathological tumour grade, high-grade tumours being significantly more likely to express PLK3 than low-grade tumours." (PMID 14970859, 2004). "The overexpression of either isoenzyme had an impact on patient prognosis with shortened survival time for patients with tumours positive for PLK1 (P=0.02) and PLK3 (P=0.02), but only PLK1 expression remained a prognostic factor in multivariate survival analysis (P=0.03)." (PMID 14970859, 2004). "All studies consistently reported an overexpression of PLK1 in the respective tumour tissue compared to the corresponding nontransformed tissue of origin." (PMID 14970859, 2004). "In addition, in a study utilizing a DNA vaccine model to compare the immunogenicity of G2/M-related antigens, it was observed that PLK1-immunized mice did not exhibit any anti-tumor effects." (PMID 40612941, 2025). "In addition, the combination of PLK1 inhibitors with chemotherapeutic agents such as paclitaxel, cisplatin, doxorubicin, and PARP inhibitors exhibits effective synergistic effects in cell proliferation and tumor growth in EOC." (PMID 41458961, 2025).